AKT3 (AKT serine/threonine kinase 3)
Diseases named in the same sentence as AKT3 in open-access papers (continued):
Sharing a sentence is not in itself a finding about the gene and the disease.
osteosarcoma (8 papers, 2017 to 2024). A usually aggressive malignant bone-forming mesenchymal neoplasm, predominantly affecting adolescents and young adults. "The subsequent finding in the current study demonstrated that the promoting effect of circNRIP1 on the malignant phenotype of osteosarcoma cells was related to the upregulation of the miR-532-3p target AKT3 gene by competitively binding to miR-532-3p." (PMID 34660257, 2021). "AKT3 shows an evident upregulation in osteosarcoma tissues and cells, and this upregulation potentiates cell proliferation as well as inhibiting cell cycle arrest at the G0/G1 phase." (PMID 34660257, 2021). "Overall, our study indicates that BMSC-EVs can transfer circNRIP1 to osteosarcoma cells and promote the progression of osteosarcoma by regulating the miR-532-3p/AKT3/PI3K/AKT axis." (PMID 34660257, 2021). "Then, the location of these genes in the signaling pathway was labeled with the results showing that AKT3 was at the core, and it was highly expressed in osteosarcoma." (PMID 34660257, 2021). "The findings collected from this study supported the promoting effect of circNRIP1 encapsulated by BMSC-EVs on the progression of osteosarcoma via regulating the miR-532-3p/AKT3/PI3K/AKT pathway." (PMID 34660257, 2021). "Meanwhile, Pearson’s correlation coefficient revealed a positive correlation between circNRIP1 and AKT3 in osteosarcoma tissues." (PMID 34660257, 2021). "Meanwhile, AKT3 has been detected to be increased in human osteosarcoma tissues and cells, and conversely, its reduction by miR-485-3p results in repressed cancer cell proliferation, migration, and invasion, which is very much in accordance to our results." (PMID 34660257, 2021). "In osteosarcoma, miR-1258 inhibits cell proliferation and promotes cell cycle to be arrested in the G0/G1 phase through targeting AKT3." (PMID 32733928, 2020). "RT-qPCR data presented an enhancement of AKT3 mRNA expression in osteosarcoma tissues." (PMID 34660257, 2021). "We therefore proposed a hypothesis that circNRIP1 delivered by bone marrow mesenchymal stem cell–derived EVs (BMSC-EVs) may augment osteosarcoma development involving the interaction with miR-532-3p, AKT3, and PI3K/AKT." (PMID 34660257, 2021). "Co-culture data showed that BMSC-EVs could transfer circNRIP1 into osteosarcoma cells where it competitively bound to miR-532-3p and weakened miR-532-3p’s binding ability to AKT3." (PMID 34660257, 2021). "Because Akt3 appears to be predominantly expressed in the brain, we used the specific inhibitors to block PI3Kα, PI3Kβ, PI3Kγ, PI3Kδ, Akt1 and Akt2 activity and studies the effects of each isoform of PI3Ks and Akts in osteosarcoma cell migration in this study." (PMID 28289332, 2017). "Osteosarcoma cell glycolysis, proliferation, migration and invasion were suppressed by decreasing glycolysis-related proteins and migration-related proteins via the inhibition of c-MET and AKT3/mTOR." (PMID 38396845, 2024). "In Osteosarcoma, hsa_circ_001569 overexpression contributed to cisplatin resistance through the Wnt/β-catenin pathway, and similarly, in CRC, hsa_circ_0007031 and hsa_circ_0000504 overexpression promoted 5-FU resistance through the circRNA/miR-885-3p/AKT3 axis." (PMID 34162394, 2021).
pancreatic cancer (8 papers, 2018 to 2024). "Thus, pancreatic carcinoma cell lines expressing only mutated and thus active K-Ras showed enhanced Akt3 expression." (PMID 38291468, 2024). "Our study shows for the first time, that Akt3 supports K-Ras(V12)-induced E-cadherin as well as NCAM expression in PANC-1 pancreatic carcinoma cells." (PMID 38291468, 2024). "Gene expression data from the cancer cell line encyclopedia (CCLE) assessing global Met expression along with its ligand, HGF, and other downstream kinases (MAPK1, AKT2, and AKT3) supported high Met expression in pancreatic cancer cell lines." (PMID 31903112, 2020). "AKT3 mRNA expression has been reported previously in pancreatic cancer cells." (PMID 38920688, 2024). "AKT1 appears to contribute more to pancreatic cancer growth whereas AKT2 and AKT3 contribute more to phosphorylating downstream targets." (PMID 38920688, 2024). "In the presented study we have analyzed the effect of oncogenic K-Ras(V12) on PI3-K-Akt signaling and discovered Akt3 as a regulator of E-cadherin and NCAM expression in PANC-1 pancreatic carcinoma cells." (PMID 38291468, 2024). "For instance, in pancreatic cancer progression, circ_0086375 could function as a sponge for miR-486-5p and could regulate the process of pancreatic cancer progression through miR-486-5p, circ-AKT3 could act as a sponge for miR-296-3p to further regulate the development of renal cell carcinoma." (PMID 37553672, 2023). "In conclusion, especially Akt3 might be involved in the K-Ras(V12) - PI3-Kα - Akt mediated regulation of E-cadherin and NCAM in PANC-1 pancreatic carcinoma cells." (PMID 38291468, 2024). "Depletion of Akt3 markedly downregulated both E-cadherin and NCAM expression on protein as well as mRNA level in the K-Ras(V12)-overexpressing PANC-1 cells, thus classifying Akt3 as a key mediator of oncogenic K-Ras-modulated cell-cell adhesion in pancreatic carcinoma cells." (PMID 38291468, 2024).
papillary thyroid cancer (8 papers, 2018 to 2022). "For example, in papillary thyroid carcinoma tissues and cells, AKT3 expression is elevated; miR-203 represses the malignancy of papillary thyroid cancer cells by downregulating AKT3." (PMID 36593867, 2022). "However, their bioinformatics analysis based on gene chips showed that AKT3, nuclear factor of activated T-cells, cytoplasmic 2 (NFATc2), and protein phosphatase 3 catalytic A (PPP3CA) were potential targets of HSDL2 in papillary thyroid cancer." (PMID 32211805, 2020). "The up-regulation of miR-29a obviously decreased AKT3 expression, via directly binding to the 3′-UTR of AKT3, thereby suppressing PI3K/AKT pathway activation, which were involved in multiple cellular functions in papillary thyroid carcinoma (PTC)." (PMID 29217524, 2018).
epilepsy (7 papers, 2016 to 2021). A brain disorder characterized by episodes of abnormally increased neuronal discharge resulting in transient episodes of sensory or motor neurological dysfunction, or psychic dysfunction. "Focal cortical dysplasia type II results from somatic brain mutations in mechanistic target of rapamycin pathway activators MTOR, AKT3, PIK3CA and RHEB and is a major cause of drug-resistant epilepsy." (PMID 34632383, 2021). "Upstream and downstream molecules involved in serine/threonine kinase AKT pathways, including Akt3, were found to be involved in epilepsy pathophysiology." (PMID 27193124, 2016). "Furthermore, mutations in other genes in the PI3K/Akt/mTOR pathway, including AKT3, PIK3CA, and DEPDC5, may also cause epilepsy." (PMID 34040629, 2021). "Comparison of the number of epileptic patients who had AKT3 deleted (n = 11/27) or spared (n = 25/27) and the absence of seizures in patients with deletion restricted to this gene confirmed that AKT3 was not involved in epilepsy." (PMID 28283832, 2017).
lung fibrosis (7 papers, 2017 to 2025). "Autoantibodies against PIP4K2B and AKT3 show increased risk of skin and lung fibrosis in patients with SSc." (PMID 40843700, 2025). "Autoantibodies against PIP4K2B and AKT3 are increased risk of skin and lung fibrosis in patients with SSc." (PMID 40843700, 2025). "By focusing on screening genes associated with the RUNX1-binding promoter region and genes with the ability to promote ARDS-associated pulmonary fibrosis, we successfully found out that AKT3 is a downstream target gene of RUNX1." (PMID 38267920, 2024). "Anti-Phosphatidylinositol-5-phosphate 4-kinase type 2 beta (PIP4K2B)- and anti-AKT Serine/Threonine Kinase 3 (AKT3)-antibodies should be further explored to confirm their association with skin and lung fibrosis in SSc patients." (PMID 36982700, 2023). "Anti-AKT3 showed higher prevalence in patients with lung fibrosis (p = 0.014) and in patients with active skin fibrosis (i.e., mRSS score > 15, p = 0.012)." (PMID 36982700, 2023). "Our findings elucidate the mechanism of the pro-autophagic and anti-fibrotic effects of miR-29a-3p in silicosis and indicate that the miR-29a-3p/Akt3/mTOR axis plays a crucial role in silica-induced lung fibrosis." (PMID 37511199, 2023). "miR-29b is a key repressor of renal and pulmonary fibrosis and has recently been shown to inhibit hepatic fibrogenesis by directly targeting PIK3R1 and AKT3 in hepatic stellate cells." (PMID 28174625, 2017). "Intriguingly, overexpression of miR-29a-3p was marked as an activator of protective autophagy by targeting Akt3/mTOR in transforming growth factor (TGF)-β-treated TC-1 cells, as a model of lung fibrosis, and resulted in amelioration of lung fibrosis and protection of lung epithelial cells." (PMID 39594634, 2024). "Anti-AKT3 antibodies have been detected in 38% (three out of eight) of patients with both lung fibrosis and mRSS score > 15, but in no other subgroup." (PMID 36982700, 2023).
megalencephaly (7 papers, 2017 to 2023). A congenital abnormality in which the occipitofrontal circumference is greater than two standard deviations above the mean for a given age. "Recently, germline and somatic point mutations in AKT3, PIK3R2, and PIK3CA have been detected in the megalencephaly-related syndrome, and somatic gain of function point mutations in AKT3, PIK3CA, and MTOR has also been detected in HME, the most severe type of megalencephaly." (PMID 28025777, 2017).
multiple myeloma (7 papers, 2019 to 2023). "Increased CDC25B, AKR1B1, and AKT3 expression was associated with poor multiple myeloma survival, indicating a detrimental effect of certain aging-associated gene patterns." (PMID 34831349, 2021). "Impairment of AKT3, a member of the AKT protein family, has also been linked to multiple myeloma, and mutations in the AKT3 gene have been frequently reported in de novo Philadelphia chromosome-positive AML." (PMID 34944006, 2021). "For example, hnRNPA2B1 is a potential therapeutic target in multiple myeloma through its mediation of the expression of AKT3." (PMID 37990246, 2023). "HNRNPA2B1 increased the stabilization of ILF3 mRNA through m6A modification, which in turn increased AKT3 expression to promote multiple myeloma progression." (PMID 36271283, 2022). "For instance, Akt3 impairment has been associated with multiple myeloma, and de novo Philadelphia chromosome-positive AML frequently show mutations of AKT3 and PIK3CD genes." (PMID 30787430, 2019).
vascular tumor (7 papers, 2016 to 2024). "In a previous experimental study with mice, AKT1 promoted de novo tumor formation, while AKT3 inhibited vascular tumor growth." (PMID 36286049, 2022). "Akt3 also limits vascular tumor growth through inhibition of endothelial cell proliferation and migration." (PMID 34591413, 2021). "An increase in migration was also observed in vascular tumor cells with an AKT3 knockdown." (PMID 33670586, 2021). "However, in vascular tumour cells AKT3 depletion increases whereas AKT1 depletion decreases sprouting angiogenesis and wound healing capacity, suggesting that AKT3 conversely inhibits vascular tumour growth and migration." (PMID 28082369, 2017). "Furthermore, there was no significant change in the expression of Rictor after knockdown of any AKT isoform in MDA-MB-231 cells, which had been shown to be regulated by AKT3 in vascular tumor cells." (PMID 26741489, 2016).
diabetes (6 papers, 2011 to 2025). "Several switch genes, including AKT3, LAMA2, ADCY1, RAB3A, RAPGEF4, and ABCC8, have been implicated in insulin signaling and diabetes." (PMID 36389068, 2022). "Western blot analysis of renal tissues from the different animal groups showed that FF, diabetes, or DM/FF significantly affected Akt1, Akt2, and Akt3 protein expression." (PMID 32025205, 2020). "We and others have shown that diabetes depresses retinal insulin signaling with decreased kinase activities of the insulin receptor and downstream signaling proteins including Akt1 and Akt3." (PMID 22046295, 2011). "More importantly, key genes of the respective pathways, such as AKT3, FGF2, FGF7, mitogen-activated protein kinase 4 (MAP3K4), MAP3K5, insulin receptor (INSR), AKT3, and mTOR, were also enriched in the analysis, thus explaining the link between diabetes and BCRL subjects in the present study." (PMID 36232660, 2022). "As previously demonstrated, Akt1 and Akt3 activities in the retina were reduced by diabetes." (PMID 22046295, 2011). "Akt2 KO mouse displays a diabetes-like phenotype, whereas Akt3 KO has a negative impact on brain development." (PMID 40313745, 2025). "Notably, AKT3 plays a vital role in the PI3K-AKT signaling, a potential pathway linking diabetes and AD." (PMID 36389068, 2022).
experimental autoimmune encephalomyelitis (6 papers, 2013 to 2024). An autoimmune demyelinating disease of the central nervous system that is produced experimentally in animals by the injection of homogenized brain or spinal cord in Freund's adjuvant. "It has been shown that Akt-3-deficient mice have smaller brains with suppressed inflammatory responses in experimental autoimmune encephalomyelitis." (PMID 24225433, 2013). "Lack of Akt3 expression in mice results in a more severe clinical course during myelin-oligodendrocyte glycoprotein (MOG)-induced experimental autoimmune encephalomyelitis (EAE)." (PMID 31404142, 2019). "In a model of myelin-oligodendrocyte glycoprotein–induced experimental autoimmune encephalomyelitis (EAE), Akt3-/- mice were more severely affected than wild-type mice." (PMID 27193124, 2016).
Hirschsprung disease (6 papers, 2017 to 2021). Hirschsprung disease (HSCR) is a congenital intestinal motility disorder that is characterized by signs of intestinal obstruction due to the presence of an aganglionic segment of variable extent in the terminal part of the colon. "In Hirschsprung disease, the level of AKT3 scaled up with that of circ-ZNF609, while miR-150-5p expression was inversely associated with circ-ZNF609 and AKT3." (PMID 31484561, 2019). "For example, in Hirschsprung’s disease, circRNA ZNF609 functions as a competitive endogenous RNA (ceRNA) to regulate AKT3 expression by sponging miR-150-5p." (PMID 29383123, 2017).
metastatic melanoma (6 papers, 2012 to 2025). A melanoma that has spread from its primary site to another anatomic site. "Increased activation of Akt3 plays an important role in the development of more aggressive tumors, and detection of Akt3 expression and activity in metastatic melanoma has shown elevated expression in 43-60% of advanced metastatic melanoma cases." (PMID 40356756, 2025). "Activated AKT3 has been detected in 43–60% of sporadic metastatic melanoma when compared to normal melanocytes, an observation attributed to increased copy number of the AKT3 gene." (PMID 23372575, 2012). "The increased activation of Akt3 plays an important role in the development of more aggressive tumors, and the detection of Akt3 expression and activity in metastatic melanoma indicates that it is upregulated in 43%-60% of advanced metastatic melanoma." (PMID 40356756, 2025). "Relative to AKT1, AKT3 was upregulated and AKT2 downregulated in all the VGP and metastatic melanoma cell lines tested." (PMID 25595898, 2015). "In metastatic melanomas, it has been reported in the past that the selective activation of Akt3, but not Akt1/2, increases the survival rate of tumorigenic cells and tumor development in 40–60% of non-familial melanomas." (PMID 32962144, 2020).
metastatic tumors (6 papers, 2016 to 2023). "In contrast, although the Akt3 levels were low in primary prostate tumors, metastatic tumor levels were even lower in 6 out of 8 patients." (PMID 34591413, 2021). "One of the other 2 patients with increased levels of Akt3 in metastatic tumors had extremely high levels of Akt1 (7.61-fold compared to primary tumors) and Akt2 (4.68-fold compared to primary tumors)." (PMID 34591413, 2021). "The metastatic tumors retained most of the genetic variants found in the original tumors, but some cases had additional CNVs, including copy number gains for the KRAS, AKT3, RICTOR, FGFR, and FANCD2 genes, and copy number losses for the MYC and RAD50 genes." (PMID 34422662, 2021). "Briefly, levels of Akt1 and Akt2 were increased in metastatic tumors compared to primary prostate tumors, while levels of Akt3 decreased." (PMID 34591413, 2021). "Akt1 KD mice had the fewest metastatic abdominal tumors, while both Akt2 KD and Akt3 KD mice had greater metastatic disease than control mice." (PMID 27533079, 2016). "Conversely, Akt2−/− and Akt3−/− had increased metastatic tumors, compared to controls." (PMID 27533079, 2016).
non-small cell lung carcinoma (6 papers, 2008 to 2025). A group of at least three distinct histological types of lung cancer, including non-small cell squamous cell carcinoma, adenocarcinoma, and large cell carcinoma.
renal cell carcinoma (6 papers, 2016 to 2025). "IPA confirmed that the target molecules identified in our study (ERK, FOXO1, FOXO3, JNK1, PDCD4, AKT3) form an interactive network with shikonin, which further leads to renal cancer, renal cell carcinoma, and apoptosis." (PMID 41462911, 2025). "The in vitro and in vivo experiments revealed that circ-AKT3 acts as a sponge of miR-296-3p to upregulate E-cadherin, resulting in reduced migration and invasion of renal cell carcinoma." (PMID 31672157, 2019). "For instance, circ-AKT3 regulates miR-296-3p/E-cadherin signaling in diabetic nephropathy, while circ-EGLN3 influences miR-1299/IRF7 in renal cell carcinoma (RCC)." (PMID 41194001, 2025).
brain malformation (5 papers, 2015 to 2024). "A comprehensive study on 33 children with pediatric epilepsy identified germline mutations (PTEN) or mosaic activating mutations (PIK3CA and AKT3) in PI3K pathway genes which dramatically manifests as different forms of brain malformations like megalencephaly and cortical dysplasia." (PMID 31507376, 2019). "Gene-specific recommendations were recently reported for PIK3R1, and for AKT3, MTOR, PIK3CA and PIK3R2 by the ClinGen Brain Malformation Variant Curation Expert Panel." (PMID 38778413, 2024). "In a third case, a somatic missense variant in this gene indicated that the somatic activation of AKT3 was responsible for this brain malformation." (PMID 35563270, 2022). "Variants in PI 3-kinases and their regulatory subunits, PIK3CA, PIK3R2 as well as one of their downstream targets, AKT3, have all been implicated in PMG and associated brain malformation phenotypes." (PMID 25855803, 2015).
cervical cancer (5 papers, 2015 to 2022). A primary or metastatic malignant neoplasm involving the cervix. "Among them, c-Rel affects the occurrence and progression of cervical cancer during whole HPV16 infection stage through miR133a-3p–modulated mir-379-369 cluster with a positive feedback way which targeted c-Rel itself and its positive regulator AKT3." (PMID 36457028, 2022). "Among them, c-Rel affects the occurrence and progression of cervical cancer during whole HPV16 infection stage through miR133a-3p–modulated mir-379-369 cluster with a positive feedback way through c-Rel itself and miR329-5p target gene AKT3." (PMID 36457028, 2022).
cognitive deficits (5 papers, 2017 to 2026). "It has also been suggested that PI3K/Akt3 play a role in attenuation of cognitive deficits in rats with induced ischemic stroke." (PMID 33142695, 2020).